NFE2L2 (NFE2 like bZIP transcription factor 2)
Diseases named in the same sentence as NFE2L2 in open-access papers (continued):
Sharing a sentence is not in itself a finding about the gene and the disease.
lymphoma (1 paper, 2023). A malignant (clonal) proliferation of B- lymphocytes or T- lymphocytes which involves the lymph nodes, bone marrow and/or extranodal sites. "Therefore, based on the present and previous studies, it seems that proper activation of NFE2L2 is required to sustain lymphoma cell survival and regulate KSHV lytic cycle activation." (PMID 37511362, 2023). "Regarding this lymphoma, it has been shown that NFE2L2 could control the KSHV latent/lytic switch and that its activation by dimethyl fumarate could induce a cytotoxic effect against PEL cells, as we have previously demonstrated." (PMID 37511362, 2023). "At the molecular level, we found that NFE2L2 and STAT3 converged in the regulation of several pro-survival molecules and in the activation of processes essential for the adaption of lymphoma cells to stress." (PMID 37511362, 2023). "The findings of this study suggest that the concomitant inhibition of NFE2L2 and STAT3 may be considered a therapeutic option for the treatment of this lymphoma that poorly responds to chemotherapies." (PMID 37511362, 2023).
macular degeneration (1 paper, 2024). Loss of vision in the central portion of the retina (macula), secondary to retinal degeneration. "In summary, targeting NFE2L2 and REV-ERBα signaling can be ideal therapeutic approaches against oxidative stress-induced macular degeneration." (PMID 38790673, 2024).
malignant glioma (1 paper, 2025). A grade III or grade IV glioma arising from the central nervous system. "Notably, the expression of NFE2L1 was significantly elevated in malignant glioma cells and Mono/Macrophages compared with that of NFE2L2 and NFE2L3." (PMID 40677211, 2025).
mastitis (1 paper, 2025). Inflammation of breast tissue during lactation or postpartum due to an obstructed duct or infection. "In both in vivo and in vitro studies, niacin can activate the AMPK/NFE2L2 signaling pathway to alleviate mastitis in dairy cows." (PMID 40429928, 2025).
medulloblastoma (1 paper, 2014). A malignant, invasive embryonal neoplasm arising from the cerebellum. "Nfe2l2 (Nuclear factor erythroid 2-related factor 2) and Pax3 (paired box gene 3) influence Srebf1 expression in mouse liver and human medulloblastoma cell line." (PMID 24806461, 2014).
metastatic disease (1 paper, 2020). "Research has now shown that mutations in KEAP1 and NFE2L2 are often associated with late-stage metastatic disease, with stage-4 cancer patients showing higher NRF2 activity than stage-3 patients." (PMID 33276631, 2020).
multiple myeloma (1 paper, 2022). "LMK235 at concentrations of 1–5 μM showed potent antimyeloma activity and downregulated heme oxygenase-1, which is an NFE2L2 transcription factor-regulated gene that may be a potential target for chemoresistant multiple myeloma treatment." (PMID 36139696, 2022).
neuroendocrine tumors of the (1 paper, 2019). "In lung tumors the deregulation of this pathway is mainly related to point mutations of KEAP1 and NFE2L2 genes and KEAP1 promoter hypermethylation, but these two genes have been rarely investigated in low/intermediate grade neuroendocrine tumors of the lung." (PMID 31126053, 2019).
neuropathy (1 paper, 2017). A disorder affecting the nervous system that manifests with pain, tingling, numbness, and/or muscle weakness. "In Neuropathy the expression of NFE2L2 & HMOX1 is down-regulated in sciatic nerves of diabetic mice and its expression aids in reduction of formalin induced inflammatory pain and thereby indicating its role in preventing sensory motor alterations." (PMID 28761062, 2017).
orchitis (1 paper, 2021). Inflammation of one or both testes due to viral or bacterial infections. "Possibly as a compensation, androgen receptor Ar, estrogen receptor Esr1, LH receptor Lhcgr, and Nfe2l2 were all increased during orchitis." (PMID 35111154, 2021). "On the other hand, Klf2, Klf4, Nfe2l2/Nrf2, Id1, Id2, Rad21, Xrcc1, and Cycs were found to be negatively correlated with androgen synthesis during orchitis." (PMID 35111154, 2021).
ovarian adenocarcinoma (1 paper, 2025). An adenocarcinoma that arises from the ovary. "Treatment with CUR alone significantly inhibited the growth of human ovarian adenocarcinoma SKOV-3/CDDP CDDP-resistant subline cells by inhibition the gene expression of the antioxidant enzymes (SOD1, SOD2, GPX1, CAT, and HO1), transcription factor NFE2L2 and signaling pathway (PIK3CA/AKT1/MTOR)." (PMID 39859517, 2025).
premature ovarian failure (1 paper, 2023). "The knockdown of the Nfe2l2 gene impaired the ovarian function and antioxidant capacity in premature ovarian failure in mice, and the activation of its pathway alleviated the oxidative stress induced by cryopreservation of the ovarian tissue." (PMID 37761983, 2023).
squamous non-small cell lung cancer (1 paper, 2024). "Sapanisertib continues in limited clinical development, primarily focusing on patients with squamous non-small cell lung cancer with KEAP1/NRF2 (NFE2L2) mutations." (PMID 39510293, 2024).
synucleinopathies (1 paper, 2022). "The OpenTargets DB reveals common association of NFE2L2, NQO2, and MAO-B withseveral NDs, displaying visible convergence for PD and AD phenotypesas tauopathies and synucleinopathies." (PMID 35245051, 2022). "All NFE2L2,NQO2, and MAO-B converge in AD and PD disorders, as well as associatedtauopathy and synucleinopathy labels." (PMID 35245051, 2022).
thyroid papillary cancer (1 paper, 2020). "In order to evaluate the involvement of VEGFA, NFE2L2, hsa-miR-17-5p, and hsa-miR-612 in thyroid pathology, we examined tissue samples from colloid goiter, papillary thyroid cancer (PTC), and a normal thyroid." (PMID 32824922, 2020). "The present study shows that tissues affected by papillary thyroid cancer or colloid goiter, and their respective adjacent tissues present increased expression of VEGFA and NFE2L2, thereby providing evidence that vascularization and oxidative stress are imbalanced in these tissues." (PMID 32824922, 2020).
tuberculosis (1 paper, 2021). A chronic, recurrent infection caused by the bacterium Mycobacterium tuberculosis. "Our study aimed to investigate the association of single nucleotide polymorphisms of NFE2L2 with tuberculosis (TB) and latent tuberculosis infection (LTBI) and the underlying causal mechanisms." (PMID 34108963, 2021).
cancer (408 papers, 2008 to 2026). A tumor composed of atypical neoplastic, often pleomorphic cells that invade other tissues. "NFE2L2, a well-established regulator of oxidative stress responses and xenobiotic detoxification, previously implicated in chemoresistance across multiple cancer types, emerged as a central hub." (PMID 41492468, 2026). "Single-cell and virtual knockout analyses revealed that cancer epithelial cells evade ferroptosis via NFE2L2-associated antioxidant defenses, which strongly correlates with immune exclusion." (PMID 42196424, 2026). "Integrating NFE2L2-associated ferroptosis regulation into cancer therapies is critical for advancing the clinical potential of this research in oncology." (PMID 39534872, 2024). "Conversely, cancer cells become more drug sensitive when NFE2L2/Nrf2 is overexpressed because it causes chemoresistance in HCC, whereas medication sensitivity is caused by downregulation of USP7, which also inhibits HCC cell proliferation and metastasis." (PMID 39463763, 2024). "NFE2L2, the master regulator of antioxidant response, is closely associated with cancer cell survival, drug resistance, and metastasis." (PMID 39767718, 2024). "Loss of the interaction on account of mutation of the KEAP1-binding TGE motif in NFE2L2 leads to increased abundance of NFE2L2 and results in the resistance of cancer cells to reactive oxygen species." (PMID 39009827, 2024). "Among the cancer-associated proteins we found five hotspot mutations conferring loss (NFE2L2 E79V/Q) or gain (PMS2 R107W, MUTYH S321L, CTNNB1 S33F) of interactions (Dataset EV6)." (PMID 39009827, 2024). "NFE2L2 plays the role of the primary transcriptional regulator for the cell's antioxidant response controls, which are associated with cancer and drug resistance." (PMID 38514488, 2024). "Aberrant activation of NRF2 in cancer is attributed to gain-of-function mutations in the NRF2-encoding gene NFE2L2 or a loss of function of its suppressor, Kelch-like ECH-associated protein 1 (KEAP1)." (PMID 36765792, 2023). "NFE2L2 was abnormally expressed in human pan-cancer and highly linked with the degree of DNA methyltransferase expression and mismatch repair (MMR) gene mutation." (PMID 36980514, 2023). "Survival analysis stratified by cancer type in TCGA dataset revealed that there was a significant association between the frequency of NFE2L2 MU and shorter OS in LGG (HR: 7.43, 95% CI 1.81–30.38) and LUAD (HR: 2.31, 95% CI 1.25–4.27)." (PMID 37794491, 2023). "KEAP1 mutation results in constitutive activation of NFE2L2 and overexpression of its target genes, which results in cancer cell survival." (PMID 36624801, 2022). "Overall, we demonstrate that APOBEC activity can lead to mutations in NFE2L2 that have large contributions to cancer cell growth and survival, and that NFE2L2 is an attractive potential target for therapeutic intervention." (PMID 35872531, 2022). "Many of these associations group into well-known cancer pathways including the NFE2L2, RB1, MAPK, and Wnt pathways." (PMID 35382456, 2022). "The prevalence of NFE2L2 activating mutations across many solid tumors and its activation has also been linked to inhibition of the cancer cells growth by inhibiting ferroptosis." (PMID 35992146, 2022). "NFE2L2 is an oncogene in various cancers including lung, pancreas, breast, and gall bladder, and thus increased dependency on NFE2L2 in cell lines with NFE2L2(A) mutations is consistent with the oncogene addiction model." (PMID 35382456, 2022). "The KEAP1/NFE2L2 mutational status has been directly linked to the responsiveness of certain cancer types to radio- and chemotherapy." (PMID 35163828, 2022). "The KEAP1-NFE2L2 pathway is frequently perturbed in cancer with inactivating mutations in KEAP1 or activating mutations in NFE2L2 reported in more than 30% of lung squamous tumors." (PMID 35382456, 2022).
cancer (continued). "Animal studies in non-small cell lung cancer (NSCLC) show that KEAP1 deletion and NFE2L2 mutations promote cancer cell growth and a pro-survival phenotype in these cells." (PMID 34502361, 2021). "NFE2L2 mutations were identified as part of a con‐GCR in 4 cancer types: LUSC, HNSC, ESCA, and BLCA." (PMID 33769711, 2021). "For example, NFE2L2 (the most significant gene that mutated in 16% of S2 but 4% in S1) has been reported in types of cancers." (PMID 34422643, 2021). "In the current study, we found that NFE2L2 is abnormally expressed in 22 cancer types and is significantly correlated with MMR gene mutation levels and DNA methylation." (PMID 33101586, 2020). "They found that NFE2L2/KEAP1 mutations are present in various cancers, with the highest incidence found in lung squamous cell carcinoma." (PMID 33228209, 2020). "In the current study, we comprehensively analyzed the association between NFE2L2 expression and patients' prognosis in 33 cancer types." (PMID 33101586, 2020). "KEAP1/NFE2L2, a cellular pathway for sensing and responding to oxidative stress, is frequently mutated in human cancers." (PMID 32839463, 2020). "Several mutations involve directly the NFE2L2 gene and are highly conserved among different cancer types." (PMID 33233657, 2020). "Specifically, NFE2L2 appeared to be a risk factor in 4 cancer types: ACC (P = 0.0016, HR = 1.03), LGG (P < 0.0001, HR = 1.03), PAAD (P = 0.0076, HR = 1.01), and UCS (P = 0.00019, HR = 1.02)." (PMID 33101586, 2020). "KEAP1, and NFE2L2 somatic mutations have been identified and characterized in various human cancers, including lung, liver, renal, and squamous cell cancers, leukemia, and others." (PMID 31428048, 2019). "In recent years, frequent mutations in the NFE2L2/KEAP1/CUL3 pathway had been reported in many types of cancers, including ESCC10,18–21." (PMID 29127303, 2017). "Each NFE2L2 variant that was detected in the patients has previously been reported as a somatic cancer-related pathogenic change in several tumor species." (PMID 29018201, 2017). "NFE2L2 thus probably causes the shift of the cellular metabolic program to promote tumorigenesis in cancer types driven by its alterations." (PMID 26792175, 2016). "Contrasting with these observations, a recent study demonstrated that lower NFE2L2 expression is associated with poorer outcome in cancer using datasets obtained from the TCGA and GEO databases." (PMID 27770790, 2016). "There are many reported cancer cases with high NFE2L2 expression, some of which are associated with increased tumourigenesis and therapy resistance and a few correlated with poor survival." (PMID 27770790, 2016). "We were also interested in evaluating NFE2L2 mRNA expression in relation to BRAF and KRAS mutations, since mutations to these genes occur frequently in PTC, and mutated KRAS and BRAF are associated with increased transcription of NFE2L2 in other cancers." (PMID 24138990, 2013). "Specifically, as cancers with pre-existing KEAP1 or NFE2L2 mutations exhibit constitutive NRF2 activation, they will not benefit from NRF2 induction by G12Ci drugs, while in contrast, tumours with wild-type KEAP1-NRF2 will benefit from G12Ci-induced NRF2 activation." (PMID 40890297, 2025). "In GC, the expression of NFE2L2 has been linked to several aggressive cancer characteristics, such as larger tumor size, increased tumor depth, lymph node metastasis, lymphovascular invasion, higher tumor stage, and poorer survival, and is also linked to resistance to 5‐FU–based chemotherapy." (PMID 40926327, 2025). "Furthermore,NFE2L2-mutated cancers often display concurrent alterations, and ongoing clinical trials (NCT05275673, NCT04518137) are evaluatingNFE2L2as a potential therapeutic target." (PMID 38628662, 2024). "Furthermore, in NSCLC and other cancer cohorts, patients with NFE2L2 mutation demonstrated more objective responses to ICIs than patients with wild type." (PMID 37794491, 2023).
cancer (continued). "Moreover, there was a significant association between the frequency of NFE2L2 MU and objective response rates to ICIs across multiple cancer types (r = 0.46; p = 0.015)." (PMID 37794491, 2023). "Similar findings were obtained in cancer patients carrying the NFE2L2 mutation." (PMID 37794491, 2023). "To investigate the predictive efficacy of NFE2L2 MU for ICI treatment in pan-cancer, we evaluated the association between NFE2L2 MU and clinical outcomes in multiple types tumors of a pooled cohort (n = 2611) composed of DFCI, MSK, MSK1661, OAK, Pender, POPLAR and PUCH cohorts." (PMID 37794491, 2023). "Moreover, APOBEC-driven mutations to NFE2L2 are also substantial contributors to cancer proliferation and survival, including R34P, E79Q, G31A, and R34G." (PMID 35872531, 2022). "Many of these associations group into well-known cancer pathways such as NFE2L2, RB1, and MAPK." (PMID 35382456, 2022). "Furthermore, 16 of the associations group into three well-known cancer pathways (NFE2L2, RB1, and MAPK)." (PMID 35382456, 2022). "Several upcoming clinical trials are designed to explore the therapeutic benefit of compounds that inhibit NRF2 in advanced cancer patients harboring mutations in NFE2L2 or KEAP1 (ClinicalTrials.gov, NCT02417701; ClinicalTrials.gov, NCT04267913; ClinicalTrials.gov, NCT03872427)." (PMID 33769711, 2021). "However, Nrf2 levels are high in different types of cancer induced by several mechanisms, including mutations in the NFE2L2 and KEAP1 genes or Keap1 inhibition by oncometabolites." (PMID 34206503, 2021). "Indeed, cancers harboring mutations in the NFE2L2 gene and featuring NRF2 constitutive activation show increased proliferation, anchorage-independent growth, and metastatic potential, dependent on mTORC1 activation." (PMID 33233657, 2020). "In a similar fashion, NFE2L2 underwent a more recent gene duplication at the level of vertebrates, but the newly emerged paralog did not retain the two linear motifs that are primarily targeted by cancer mutations." (PMID 32731489, 2020). "For instance, KEAP1 encodes the adapter protein of an E3 ligase complex which can ubiquitinate NRF2, and previous studies have proven that mutations in KEAP1 and NFE2L2 may lead to NRF2 activation which may further contribute to spontaneous cancer development." (PMID 32434476, 2020). "It is now well known that loss-of-function mutations of the KEAP1 gene or gain-of-function mutations in NFE2L2 enhance the resistance of cancer cells to anticancer drugs, such as etoposide and carboplatin, and it is associated with poor outcome of platinum-based advanced NSCLC patients." (PMID 29643973, 2018). "In human cancers, similar to NFE2L2, KEAP1 mutations would disrupt the normal combination of NFE2L2 and KEAP1 in tumors, resulting in accumulation of excessive intracellular NFE2L2 and activation of its downstream genes and the eventual promotion of tumor growth." (PMID 29484121, 2018). "Because of its strong association with cancer, we hypothesized that NFE2L2-mediated genes could be used to indicate cancer progression." (PMID 26596768, 2015). "To address whether the NFE2L2-mediated genes (1765 differentially expressed genes) are statistically significantly associated with KEGG cancer pathways, we conducted a resampling test." (PMID 26596768, 2015). "While the presence of NFE2L2 mutations may result in a lower number of immune cells, there is potential for adoptive T cell therapy to enhance the efficacy of immunotherapy in NFE2L2 mutated cancers." (PMID 37794491, 2023). "The stage of cancer at which mutations in NFE2L2 and KEAP1 arise is currently unknown." (PMID 33276631, 2020). "Several of these genes, including KEAP156,57,58 and EP300,59,60,61 are well-known cancer drivers or regulators of NFE2L2 activity, and targeting this axis has recently been implicated in re-sensitization strategies." (PMID 41492468, 2026).